TIAM1 (TIAM Rac1 associated GEF 1)
Diseases named in the same sentence as TIAM1 in open-access papers (continued):
Sharing a sentence is not in itself a finding about the gene and the disease.
oral squamous cell carcinoma (3 papers, 2018 to 2024). "In fact, Tiam1 has been shown to enhance proliferation, invasion, and metastasis in oral squamous cell carcinoma (Zhou et la, 2017)." (PMID 36446524, 2023). "It was recently found that Tiam1 promotes proliferation, invasion, and metastasis in oral squamous cell carcinoma cells by binding with Semaphorin 4D." (PMID 29416753, 2018). "Tiam1 has been reported as a potential oncogene in oral squamous cell carcinoma." (PMID 38946720, 2024).
osteosarcoma (3 papers, 2015 to 2021). A usually aggressive malignant bone-forming mesenchymal neoplasm, predominantly affecting adolescents and young adults. "Depletion of Tiam1 or Pak2 in U2OS (human osteosarcoma) cells also led to increased intercentrosomal distance in prophase." (PMID 26078008, 2015).
schizophrenia (3 papers, 2016 to 2024). A major psychotic disorder characterized by abnormalities in the perception or expression of reality. "RAC1 can be also involved in the pathogenesis of schizophrenia as the downstream signaling hub molecule for the proteins encoded by risk genes such as DISC1, KALRN, and TIAM1." (PMID 34943902, 2021).
squamous cell carcinoma (3 papers, 2016 to 2020). A carcinoma arising from squamous epithelial cells. "Taken together, our results indicated that Rab23 promotes squamous cell carcinoma cells migration and invasion by regulating Integrin β1/Tiam1/Rac1 pathway." (PMID 26716504, 2016). "Interestingly, expression of Tiam1 WT and P-Rex1 WT, but not their GEF* mutants, in the epithelial squamous cell carcinoma cell line, A431, and the epithelial immortalized Madin-Darby canine kidney cell line, MDCKII, resulted in phenotypic effects similar to those observed in NIH3T3 cells." (PMID 26887924, 2016).
Alzheimer disease (2 papers, 2019 to 2021). A progressive, neurodegenerative disease characterized by loss of function and death of nerve cells in several areas of the brain leading to loss of cognitive function such as memory and language. "Therefore, we speculate that MTUS2, GTPBP6, TIAM-1 and SHROOM2 are likely associated with Alzheimer’s disease." (PMID 33525573, 2021). "In addition, Tiam1 activates and recruits to the membranes after exposure to amyloid beta peptide in hippocampal neurons, and this might exert influence to the pathology of Alzheimer disease." (PMID 31438846, 2019).
bladder cancer (2 papers, 2020 to 2021). "Rac1 activation by TIAM1 is an important component of the OPN-CD44-TIAM1-Rac1-mediated mechanism of invasion in bladder cancer cell lines." (PMID 33203146, 2020).
breast invasive carcinomas (2 papers, 2016 to 2017). "Oncoprints showed alterations (amplification, deep deletion, mRNA upregulation truncating mutation and missense mutation) of TIAM1 and VAV2 genes in invasive breast carcinomas and TNBC data sets." (PMID 27902969, 2017).
colorectal tumors (2 papers, 2013 to 2017). "In the present study, we demonstrated that introduction of Tiam1 into the germ-line caused a significant increasing of nuclear accumulation of β-Catenin, decreasing of membrane E-Cadherin, and enrichment of Vimentin in the colorectal tumors with more invasive ability." (PMID 24069171, 2013). "The stabilization and nuclear translocation of TIAM1 following APC depletion was also confirmed by immunofluorescence microscopy and is consistent with the nuclear accumulation of TIAM1 we observe in colorectal tumors and CRC cell lines with defective APC." (PMID 28416184, 2017). "In order to better understand the role and mechanism of Tiam1 in CRC metastasis in vivo, in this study, we developed pCDFl-Tiaml-copGFP-transgenic mice and induced colorectal tumor formation through treatment of DMH." (PMID 24069171, 2013). "The carcinogen DMH (20 mg/kg) was used to induce colorectal tumors though intraperitoneal (i.p.)injections once a week for 24 weeks from the age of 4 weeks on Tiam1 transgenic or non-transgenic mice." (PMID 24069171, 2013).
depression (2 papers, 2020 to 2022). "Here, we establish Tiam1 as an essential factor in the pathophysiology of comorbid depression in chronic pain through its regulation of maladaptive synaptic plasticity in ACC neurons, which can be targeted by ketamine to produce sustained antidepressant-like effects." (PMID 36519542, 2022). "Notably, administration of low-dose ketamine, an NMDAR antagonist emerging as a promising treatment for chronic pain and depression, induces sustained antidepressant-like effects in mouse models of chronic pain by blocking Tiam1-mediated maladaptive synaptic plasticity in ACC neurons." (PMID 36519542, 2022).
Down syndrome (2 papers, 2021 to 2022). "Moreover, the mammalian Tiam1 has four isoforms that are detected in the cerebral cortex and hippocampus and their expressions are increased in Down syndrome mouse model, while the function of individual isoforms in the nervous system is unknown." (PMID 36223408, 2022).
Hyperglycemia (2 papers, 2015 to 2018). An increased concentration of glucose in the blood. "Our findings suggest that: [i] inhibition of Tiam1-Rac1-Nox2 pathway (NSC23766) significantly attenuates hyperglycemia-induced p38 MAP kinase in the retina and its capillary cells and [ii] 2-BP, an irreversible inhibitor of S-acyltransferase, markedly attenuates Rac1-Nox2-p38 MAP kinase cascade." (PMID 25967961, 2015).
invasive ductal carcinoma (2 papers, 2016). "In 20 areas of invasive ductal carcinoma, cancer-associated fibroblasts showed increased cytoplasmic OPN expression and decreased Tiam1 expression." (PMID 26821678, 2016).
ischemia (2 papers, 2010 to 2017). A hypoperfusion of the BLOOD through an organ or tissue caused by a PATHOLOGIC CONSTRICTION or obstruction of its BLOOD VESSELS, or an absence of BLOOD CIRCULATION. "Thus, it is postulated that regulation of Tiam1 and Trio following cerebral ischemia contributes to the enhanced Rac1 GTPase activation following ischemia/reperfusion." (PMID 20830300, 2010).
laryngeal squamous cell carcinoma (2 papers, 2023). A squamous cell carcinoma that arises from the larynx. "In addition, upregulation of Tiam1 expression could also promote radioresistance in laryngeal squamous cell carcinoma by activating the JNK/ATF-2 signaling." (PMID 36765039, 2023).
metastatic melanoma (2 papers, 2016 to 2022). A melanoma that has spread from its primary site to another anatomic site. "In fact, it has been shown that TIAM1 and CORO1C are negative regulators of metastatic melanoma growth." (PMID 35562405, 2022).
non-small cell lung carcinoma (2 papers, 2020 to 2023). A group of at least three distinct histological types of lung cancer, including non-small cell squamous cell carcinoma, adenocarcinoma, and large cell carcinoma. "Circular RNA circ-RAD23B promotes cell growth and invasion by targeting miR-593-3p/CCND2 and miR-653-5p/TIAM1 pathways in non-small cell lung cancer." (PMID 32228518, 2020).
papilloma (2 papers, 2013 to 2016). A benign epithelial neoplasm that projects above the surrounding epithelial surface and consists of villous or arborescent outgrowths of fibrovascular stroma. "In DMBA/TPA chemical carcinogenesis experiments, Tiam1 deficient mice showed a reduced number of papillomas but increased numbers of SCCs." (PMID 27506937, 2016). "The cancer-linked phenotype of Vav2/Vav3-deficient mice is also quite different from that previously reported for Tiam1-deficient mice during both tumor initiation and papilloma/cSCC malignant progression." (PMID 23935450, 2013). "In agreement with the described role of Tiam1, one function of Rac1 may be to transmit growth factor signals from the tumor environment which stimulate papilloma growth." (PMID 27506937, 2016).
Anxiety (1 paper, 2022). Intense feelings of nervousness, tension, or panic often arise in response to interpersonal stresses. "Together, these results suggest that Tiam1 is essential in postnatal forebrain excitatory neurons for the development of chronic pain–induced depressive/anxiety-like behaviors." (PMID 36519542, 2022). "Tiam1 in the ACC is activated in mouse models of chronic pain with depressive/anxiety-like behaviors." (PMID 36519542, 2022). "In contrast, deletion of Tiam1 from postnatal forebrain excitatory neurons prevented both depressive- and anxiety-like behaviors in mouse models of chronic pain." (PMID 36519542, 2022). "Further research is needed to determine whether Tiam1 mediates synaptic plasticity in the CeA driving chronic pain–induced anxiety." (PMID 36519542, 2022). "Since Tiam1-cKO mice develop chronic pain similar to that of control littermates, we next explored whether Tiam1 plays a role in chronic pain–induced depressive/anxiety-like behaviors by testing control and Tiam1-cKO mice 7 weeks after sham or SNI surgery." (PMID 36519542, 2022). "Likewise, in the CFA-induced inflammatory pain model, Tiam1-cKO mice displayed a marked reduction in depressive/anxiety-like behaviors compared with control mice." (PMID 36519542, 2022). "Strikingly, we found that, in contrast with SNI-treated control mice, Tiam1-cKO mice subjected to SNI did not display depressive- or anxiety-like behaviors in the FST, the TST, the sucrose-preference test (SPT), the EPM test, and the OFA test and instead performed similarly to sham-treated animals." (PMID 36519542, 2022). "Interestingly, Tiam1 deletion from ACC neurons did not affect chronic pain–induced anxiety-like behaviors, as no significant change was observed in the open-arm time in the EPM test or center-zone time in the OFA test." (PMID 36519542, 2022).
aortic aneurysm (1 paper, 2025). A ruptured aneurysm located in the wall of the proximal portion of the descending aorta proceeding from the arch of the aorta. "In aortic aneurysms, inflammatory RNS induce Septin2 S‐nitrosylation at Cys111, reducing Septin2–TIAM1 affinity and causing TIAM1 redistribution." (PMID 41020039, 2025).
bacterial pneumonia (1 paper, 2023). Acute infection of the lung parenchyma caused by bacteria (e.g., Streptococcus pneumoniae, Haemophilus influenzae, Chlamydia pneumoniae, Mycoplasma pneumoniae, and Legionella pneumophila). "This suggests that, although overall recruitment was normal, Tiam1 affects the route or speed of neutrophil recruitment during bacterial pneumonia." (PMID 38077328, 2023).
breast adenocarcinoma (1 paper, 2017). "In this study we show that the Ser179Glu mutant binds strongly Tiam1, a Rac1-GEF reducing Rac1-GTP by 3-fold in MCF-7 breast adenocarcinoma cells." (PMID 29121646, 2017).
colorectal adenoma (1 paper, 2013). An adenoma that arises from the colon or rectum. "Formation of colorectal adenoma, cancer and distant metastasis in Tiam1 transgenic mice and wild-type mice after DMH treatment." (PMID 24069171, 2013).
experimental autoimmune encephalomyelitis (1 paper, 2016). An autoimmune demyelinating disease of the central nervous system that is produced experimentally in animals by the injection of homogenized brain or spinal cord in Freund's adjuvant. "Whereas Tiam1 genetic deficiency weakens IL-17A expression partially and inhibits the development of experimental autoimmune encephalomyelitis (EAE), deletion of Rac1 in T cells exhibits more robust effects on Th17 cells and EAE." (PMID 27725632, 2016).
glioblastoma (1 paper, 2021). The most malignant astrocytic tumor (WHO grade IV). "This also promoted Lgl1 phosphorylation, indicating that the TIAM1 short isoform is able to fulfill this role in other glioblastoma cells if its expression is artificially enhanced." (PMID 34624316, 2021). "Analysis of TCGA data using TCGASpliceSeq indicates that glioblastomas more frequently express codons 18 to 29 of TIAM1 compared with the upstream codons required for full-length TIAM1 expression." (PMID 34624316, 2021). "As above, TIAM1 can redundantly fulfill this role in a subset of glioblastomas." (PMID 34624316, 2021). "This second mechanism for Lgl1 phosphorylation is probably active in only a small subset of glioblastoma patients, based on analysis of exon expression levels and comparative RNA-seq expression of PREX1 and TIAM1 mRNA in 152 patients in the TCGA database." (PMID 34624316, 2021).
HIV-1 infection (1 paper, 2010). The type species of lentivirus and the etiologic agent of acquired immunodeficiency syndrome (AIDS). "Env-mediated cell-cell fusion, virus-cell fusion and HIV-1 infection are dependent on Tiam-1, Abl, IRSp53, Wave2, and Arp3 as shown by attenuation of fusion and infection in cells expressing siRNA targeted to these signaling components." (PMID 20585556, 2010).
insular carcinoma (1 paper, 2021). "In this study, we prioritized three potentially deleterious coding variants in three genes, namely CHEK2, TIAM1, and EWSR1 in an NMTC family with aggregation of PTC, micro-PTC, and insular carcinoma." (PMID 33692755, 2021).
mental retardation (1 paper, 2010). "Therefore, further characterization of the mechanisms by which Tiam1 and other Rho-specific regulatory proteins are controlled in neurons may contribute to understand the underlying causes of mental retardation and other neurological disorders." (PMID 20333299, 2010).
mitral valve prolapse (1 paper, 2021). A fairly common and often benign valvular heart disorder characterized by redundancy or hooding of mitral valve leaflets so that they prolapse into the left atrium, often causing mitral regurgitation. "TIAM1 was related to the non-syndromic mitral valve prolapse." (PMID 35141295, 2021).
mood disorder (1 paper, 2022). A cognitive disorder a disturbance in which the person's mood is hypothesized to be the main underlying feature. "Our work demonstrates the critical role Tiam1 plays in the pathophysiology of chronic pain–induced mood dysregulation and the sustained antidepressant-like effects of ketamine, revealing it as a potential therapeutic target for the treatment of comorbid mood disorders in chronic pain." (PMID 36519542, 2022). "However, we did not detect significant Tiam1 activation after SNI surgery in other brain regions that are thought to be involved in the comorbidity between pain and mood disorders, including the amygdala, nucleus accumbens (NAc), insular cortex, or prefrontal cortex (PFC)." (PMID 36519542, 2022).
multiple sclerosis (1 paper, 2016). A progressive autoimmune disorder affecting the central nervous system resulting in demyelination. "Thus, our findings highlight a regulatory pathway of Tiam1/Rac1 in Th17 cells and suggest that it may be a therapeutic target in multiple sclerosis." (PMID 27725632, 2016).
oral cancer (1 paper, 2015). "In a larger study with longer follow-up, we sought to confirm whether the expression of Tiam1 in several types of HNSCC, especially oral cancer, was associated with disease progression and long-term outcomes." (PMID 26369827, 2015).
rectal cancer (1 paper, 2021). A primary or metastatic malignant neoplasm that affects the rectum. "CNV of TIAM1 only in rectal cancer was significantly correlated to mRNA RSEM of TIAM1." (PMID 34526059, 2021).
sarcoma (1 paper, 2023). A usually aggressive malignant neoplasm of the soft tissue or bone. "Interestingly, overexpression of these regulatory proteins such as CASK, TIAM1, APBA1, and NRXN, have also been linked with sarcoma progression." (PMID 36599925, 2023).
squamous cell lung carcinoma (1 paper, 2015). A carcinoma arising from squamous bronchial epithelial cells. "Indeed, we have shown here that an inverse correlation exists between TIAM1 and HUWE1 (and TIAM1 and c-MET) in squamous cell lung carcinoma." (PMID 25543140, 2015).
triple-negative breast carcinoma (1 paper, 2018). An invasive breast carcinoma which is negative for expression of estrogen receptor (ER), progesterone receptor (PR), and human epidermal growth factor receptor 2 (HER2). "Moreover, the Tiam1/Rac1 signaling axis contributes to tumorigenic progression in triple-negative breast cancer by mediating the acquisition of integrin-directed metastasis-associated tumor cell phenotypes." (PMID 29416753, 2018).
viral infection (1 paper, 2017). "TNFAIP3, ULBP1 and TIAM1 were consistently down-regulated by viral infection, while CCL8, CCL11, CXCL11, NCF2, CSF3 and PRKCB were significantly up-regulated after infection." (PMID 28938587, 2017).
α-thalassemia (1 paper, 2012). "Recent studies of a mouse model of typical α-thalassemia X-linked mental retardation (ATRX) also demonstrated increased autophosphorylation of CaMKIIα at Thr286, decreased levels of spinophilin and PP1, and increased phosphorylation of two downstream CaMKII/PP1 substrates, Tiam1 and Kalirin-7." (PMID 22348105, 2012).